PARP9 (poly(ADP-ribose) polymerase family member 9)
Diseases named in the same sentence as PARP9 in open-access papers (continued):
Sharing a sentence is not in itself a finding about the gene and the disease.
glioma (continued). "The NMRGS score of every glioma patient was obtained as follows: NMRGS score = (-0.28992*CD38 expression) + (0.38315*NADK expression) + (-0.04654*NAPRT expression) + (0.2211*NMNAT3 expression) + (-0.24486*PARP6 expression) + (0.29991*PARP9 expression)." (PMID 36845744, 2023). "In summary, this study demonstrates that PARP9 is overexpressed in glioma samples." (PMID 32678519, 2020). "However, the expression of PARP9, its clinical significance and its relationship with immune infiltration in glioma remain elusive." (PMID 32678519, 2020). "Collectively, these data suggest that PARP9 may serve as an oncogene for glioma and can promote poor prognosis." (PMID 32678519, 2020). "Therefore, to better understand the essential role of PARP9, further study of PARP9 protein levels in glioma samples is necessary." (PMID 32678519, 2020). "A Cox regression analysis with univariate and multivariate analyses demonstrated that PARP9 may be a valuable prognostic biomarker for glioma patients." (PMID 32678519, 2020). "PARP9 may serve as an unfavorable prognosis predictor for glioma and a potential immunotherapeutic target." (PMID 32678519, 2020). "Correlation analysis showed that PARP9 expression was positively correlated with 6 immune cell‐specific markers, which indicated that patients with higher PARP9 expression were more likely to have more infiltrating immune cells than patients with lower PARP9 expression in glioma." (PMID 32678519, 2020). "The results indicated that PARP9 was a poor prognosis marker in glioma." (PMID 32678519, 2020). "Thus, this study aimed to reveal the relationship between PARP9 and glioma and explore the potential prognostic value and immunotherapeutic targetability of PARP9 in glioma." (PMID 32678519, 2020). "Previous studies have also shown that PARP9 can regulate macrophages, which are the major type of immune cell within brain tumors, often comprising up to 30% of the tumor mass, indicating that PARP9 may influence tumor immune infiltration in glioma." (PMID 32678519, 2020). "In addition, it was shown that PARP9 played an important role in the immune microenvironment of glioma and that PARP9 may be a prepotential immunotherapeutic target for glioma." (PMID 36778644, 2023). "Moreover, miRNA193a-CM down regulated PARP9, which is shown to be overexpressed in human BC cells and promotes cell migration; as well as DDX60, an interferon-associated gene which is associated with glioma malignancy." (PMID 36230929, 2022). "Therefore, taken together, PARP9 may serve as an unfavorable prognosis predictor for glioma and a potential immunotherapeutic target, which, when used in combination, may improve the therapeutic efficacy of ICIs." (PMID 32678519, 2020). "DTX3L is reported to regulate the ubiquitin modification of PARP family proteins (PARP1, PARP2, PARP9, PARP14), promoting proliferation, migration and chemotherapy resistance of lymphoma, glioma, and melanoma." (PMID 38304253, 2023). "IFNAR2 and PARP9 show differences across all groups, while AFP and GFRA1 are significantly differentially expressed only between other gliomas and GBM." (PMID 36834486, 2023). "Most importantly, it proved that CD38, NMNAT2, PARP9, and BST1 might be important prognostic molecular markers and potential therapeutic targets for glioma patients." (PMID 36778644, 2023). "The four genes, PARP9, BST1, NMNAT2, and CD38, might be important molecular biomarkers and therapeutic targets for glioma patients." (PMID 36778644, 2023). "In our study, we firstly performed the comprehensive research to identify the expression pattern and distribution of PARP9 in 1,114 glioma samples, which include, but are not limited to, lower‐grade gliomas." (PMID 32678519, 2020). "By analyzing the RNA sequencing data of glioma and normal brain tissue from the TCGA database, we found that PARP9 was significantly upregulated in glioma compared to nontumor tissues (P < .001)." (PMID 32678519, 2020).
prostate carcinoma (10 papers, 2016 to 2025). A carcinoma that arises from epithelial cells of the prostate gland. "Parp9 is reported to be involved in promoting the proliferation, survival, and chemotherapy resistance in lymphoma and prostate cancer, and its over-expression in human breast cancer is associated with cancer cell migration." (PMID 38660676, 2024). "The overexpression of PARP9 has been demonstrated to positively correlate with the pathological progression of lymphoma, breast cancer, and prostate cancer." (PMID 36845744, 2023). "PARP9 has been shown to contribute to tumor recurrence, metastasis, and resistance to chemotherapy in prostate cancer." (PMID 32678519, 2020). "The increase in IRF1 and inhibition of proliferation following PARP9 silencing have also been observed in prostate cancer models, as well as a reduction in proliferation and chemo resistance following PARP9 or PARP14 inhibition, in both a STAT-1-dependent and independent manner, respectively." (PMID 41463260, 2025). "To test whether Dtx3L/Parp9 contributes to AR-regulated gene expression in prostate cancer cells, we engineered VCaP cells with a Dox-inducible shRNA to Dtx3L and used the lines for transcriptomic analysis." (PMID 33976187, 2021). "Furthermore, androgen induces the association of AR with the DTX3L-PARP9 heterodimer, where PARP9, using its macrodomains (MD1 and MD2), binds to the ADP-ribose moieties on AR deposited by PARP7, thus modulating AR transcriptional activity both positively and negatively in prostate cancer cells." (PMID 40128585, 2025). "The crosstalk between IFN and androgen signaling appears to be bidirectional given that IFN can induce Dtx3L/Parp9, and AR can repress IFN signaling through induction of genes such as SOCS3 in prostate cancer cells." (PMID 33976187, 2021). "Of note, genetic inhibition of PARP9 and PARP14 was shown to increase chemotherapy efficacy in prostate cancer cells." (PMID 27791205, 2016).
breast carcinoma (9 papers, 2018 to 2025). "PARP9 is also implicated in breast cancer progression, particularly in tumor immune evasion." (PMID 40741921, 2025). "In fulvestrant-resistant breast cancer cells, PARP9 depletion disrupts the PI3K–AKT pathway, leading to PD-L1 downregulation and a reduction in both chemoresistance and immune escape." (PMID 40741921, 2025). "The results indicated that PARP9 expression was significantly elevated in several malignancies, including gastric cancer, breast cancer, cervical squamous cell carcinoma, and cervical adenocarcinoma." (PMID 39739965, 2024). "The levels of PARP9 are also elevated in breast cancer and its depletion inhibited the migration of breast cancer cells." (PMID 35096828, 2021). "Knockdown of PARP9 was indicated to inhibit the migration of breast cancer cells, which suggested that PARP9 may promote breast cancer progression." (PMID 32678519, 2020). "Notably, SOX6 has been shown to exert a influence in cervical cancer, breast cancer, and gastric cancer, while our study revealed that SOX6 levels decreased with diminishing PARP9 expression." (PMID 39739965, 2024). "The mRNA levels of TGM2, SASH1, PARP9, STAT1 and ANXA1 were not significantly different between ER+ and ER--breast cancer tissues." (PMID 29416786, 2018).
lymphoma (8 papers, 2010 to 2024). A malignant (clonal) proliferation of B- lymphocytes or T- lymphocytes which involves the lymph nodes, bone marrow and/or extranodal sites. "Such viral antagonism could not only inform us of the role for macro-PARPs in the cells, but could also be used as a guide to devise useful interventions for treatment of the aggressive lymphomas that are associated with high PARP9 expression." (PMID 24875882, 2014). "PARP14 was first described as B-cell aggressive lymphoma protein-2 (BAL2), along with PARP9/BAL1 and PARP15/BAL3, as frequently overexpressed in fatal high-risk lymphoma." (PMID 37507011, 2023). "The expression of PARP9 was shown to be induced by IFNγ, which is also triggered by IAV, and expression of PARP9 in lymphoma cells was found to increase the expression of several interferon-stimulated genes." (PMID 29980615, 2018).
cervical cancer (6 papers, 2021 to 2025). A primary or metastatic malignant neoplasm involving the cervix. "LncRNA SNHG16 recruits the transcription factor SPI1 to promote the transcription of PARP9, thereby promoting the tumorigenicity of cervical cancer cells." (PMID 35771155, 2022). "Previous study shows that SNHG16 can combine with transcription factor SPI1 to upregulate PARP9 transcription to further promote tumorigenicity of cervical cancer." (PMID 37303939, 2021). "For example, SNHG16 can recruit the SPI1 protein to promote the transcriptional activation of the PARP9 promoter in cervical cancer." (PMID 37303939, 2021). "A previous study discovered that lncRNA small nucleolar RNA host gene 16 upregulated poly(ADP-ribose) polymerase family member 9 expression by recruiting the transcription factor, SPI1, to promote the tumorigenicity of cervical cancer cells." (PMID 34738863, 2021).
COVID-19 (5 papers, 2021 to 2025). A disease caused by infection with severe acute respiratory syndrome coronavirus 2. "The hypermethylated genes with the lowest p values for hospitalized COVID-19 patients at inclusion (T1) vs. at 6 weeks post-inclusion (T2) were PARP9, ABCA1, MX1, OAS1, ARID5B, and the hypomethylated genes included TMEM131, ROCK1, IFNGR1, CFAP61, VRK2, and C6orf138." (PMID 41227320, 2025). "However, in this work, PARP9’s functional effects on COVID-19 are through its interaction with other genes (sites) and its interaction with the subgroups." (PMID 38666857, 2024). "Besides PARP9, the three genes KRT8, SEC14L1, and ALCAM have also been linked to COVID-19." (PMID 38666857, 2024). "Our transcriptomics and qPCR results indicated that a set of PARP family members, including Parp9, Parp10, Parp12, and Parp14, were significantly induced by SARS-CoV-2 infection in mice, similar to those in COVID-19 patients." (PMID 35487885, 2022). "Further, they observed that key driver genes, which were upregulated with COVID-19 and IBD inflammation (e.g., CXCL1, GBP4, SOCS3, PARP14, and PARP9), were downregulated following the use of infliximab." (PMID 36060521, 2022).
coronary artery disease (4 papers, 2016 to 2025). "PARP14 together with PARP9 are also associated with inflammation and human coronary artery disease." (PMID 39823074, 2025).
melanoma (4 papers, 2018 to 2024). A malignant, usually aggressive tumor composed of atypical, neoplastic melanocytes. "In addition to well-established IFNγ target genes such as CD274, IRF1, and B2M, three members of the PARP family—PARP9, −12 and −14—were consistently upregulated in all cell models as well as in IFNGhigh patient melanoma (comparing top 15% by IFNG expression to lowest 15% in the TCGA SKCM dataset)." (PMID 37752135, 2023). "For instance, RNA-seq analysis of human melanoma COLO829 cells transfected with MITF short hairpin RNA (shRNA) demonstrates an up-regulation of over 17 of the same 55 innate immune DEGs identified in Mitfmi-vga9/+ McSCs, including Ifih1, Ifit3, Irf7, Parp9, and Stat1 (GSE50686)." (PMID 29723194, 2018).
esophageal cancer (3 papers, 2021 to 2022). A primary or metastatic malignant neoplasm involving the esophagus. "Inhibition of circPRKCI repressed viability, colony formation, cell cycle progression of esophageal cancer and elevated cell radiosensitivity through the miR-186-5p/PARP9 axis, showing that circPRKCI played a suppressor role in RT of esophageal cancer." (PMID 35372031, 2022). "CircPRKCI depletion contributes to radiosensitivity and represses progression of esophageal cancer by the regulation of miR-186-5p/PARP9 axis." (PMID 34695805, 2021). "Circular RNA PRKCI knockdown inhibits esophageal cancer progression and elevates cell radiosensitivity through regulating the miR-186-5p/PARP9 axis." (PMID 34853591, 2021).
glioblastoma (3 papers, 2022 to 2025). The most malignant astrocytic tumor (WHO grade IV). "Elevated PARP9 expression is associated with poor prognosis in glioblastoma, indicating its role in central nervous system diseases, where excessive DNA damage response may contribute to neuronal apoptosis following a stroke." (PMID 40313968, 2025).
pancreatic cancer (3 papers, 2024 to 2025). "deciphered the role of PARP9, PARP10, and PARP14 in regulating the metabolic network and its critical cofactors (nicotinamide adenine dinucleotide (NAD) or its reduced form, NADH) in pancreatic cancer cells." (PMID 39497715, 2024).
gastric cancer (2 papers, 2024 to 2025). A primary or metastatic malignant neoplasm involving the stomach. "Subsequently, to assess the effect of SOX6 overexpression on PARP9 knockdown in gastric cancer cells, we first transfected AGS cells with a plasmid encoding SOX6 and verified overexpression efficiency via Western blot analysis." (PMID 39739965, 2024). "PARP9 is also highly expressed in gastric cancer, where it promotes the malignant behavior of gastric cancer cells." (PMID 40741921, 2025). "Further analysis through the Ualcan database corroborated these findings from TCGA data, revealing increased levels of PARP9 in gastric cancer (p = 1.6e-12)." (PMID 39739965, 2024). "Finally, ROC curve analysis confirmed that PARP9 exhibited high accuracy for predicting prognosis among gastric cancer patients (AUC = 0.913,CI: 0.875–0.950)." (PMID 39739965, 2024). "Nonetheless, the relationship between PARP9 and gastric cancer remains inadequately characterized." (PMID 39739965, 2024). "By synthesizing existing knowledge on the role of PARP9 in other tumor types and elucidating its function within gastric cancer may reveal novel therapeutic targets for managing this disease." (PMID 39739965, 2024). "The expression and prognostic significance of PARP9 in gastric cancer (GC) were examined using bioinformatics approaches." (PMID 39739965, 2024). "Mechanistic studies indicate that PARP9 interacts with SOX6, a key regulator of tumor progression, to enhance resistance to apoptosis and DNA damage, further supporting its contribution to gastric cancer pathogenesis." (PMID 40741921, 2025).
head and neck squamous cell carcinoma (2 papers, 2024 to 2025). A squamous cell carcinoma that arises from any of the following anatomic sites: lip and oral cavity, nasal cavity, paranasal sinuses, pharynx, larynx, and salivary glands. "PARP9, its binding partner DTX3L and PARP14 protein levels are significantly correlated in head and neck squamous cell carcinoma (HNSCC) and other tumour types though a mechanism where PARP9/DTX3L regulates PARP14 post-transcriptionally." (PMID 38182103, 2024). "We have explored further the molecular requirements of PARP9/DTX3L and PARP14 mediated survival using head and neck squamous cell carcinoma (HNSCC) and HeLa cell lines, which have increased PARP9/DTX3L and PARP14 expression." (PMID 38182103, 2024).
reovirus infection (2 papers, 2021 to 2024). "Importantly, liver histopathology revealed the liver from PARP9 KO mice showed more severe diffuse necrosis and loss of structural markings compared to WT littermates at day 6 after reovirus infection." (PMID 33976210, 2021). "We found that PARP9 KO mice were more susceptible to reovirus infection than their WT littermates." (PMID 33976210, 2021). "A noncanonical sensor for RNA viruses that initiates type 1 IFN response is PARP9, and deletion of PARP9 in human immune cells inhibits type 1 IFN response during reovirus infection." (PMID 38932231, 2024). "PARP9 KO BMDC exhibited more reduced p85 phosphorylation compared to WT BMDC after VSV or reovirus infection." (PMID 33976210, 2021). "As expected, compared with WT mice, PARP9 KO mice produced three- to fourfold less type I IFN following reovirus infection." (PMID 33976210, 2021). "Importantly, the physiological dsRNA species recognized by PARP9 during reovirus infection were 8 to 1187 bp of S4 gene (Reo1187), 11 to 1198 bp of S3 gene (Reo1198), 16 bp to 1320 bp of S2 gene (Reo1320), and 9 to 1410 bp of S1 gene (Reo1410)." (PMID 33976210, 2021). "Similarly, heart histology showed that the heart from PARP9 KO mice showed more severe inflammatory lesions and infiltrated cells, consistent with severe myocarditis, compared to WT littermates at day 6 after reovirus infection." (PMID 33976210, 2021). "Compared to WT BMDC, PARP9 KO or MAVS KO or both PARP9 and MAVS DKO reduced dramatically production of IFN-α and IFN-β in PARP9 KO or MAVS KO BMDC in response to stimulation with intracellular poly (I:C) or reovirus infection." (PMID 33976210, 2021). "Furthermore, we examined the phosphorylation of IRF3 and NF-κB subunit p65 in WT, PARP9 KO, MAVS KO, and PARP9/MAVS DKO BMDC after reovirus infection." (PMID 33976210, 2021). "As expected, overexpression of PARP9 in PARP9 and MAVS DKO BMDC produced significantly more IFN-α and IFN-β than those cells expressing control vector in response to intracellular poly I:C or viral dsRNA Reo1198 or reovirus infection." (PMID 33976210, 2021). "Next, we investigated if overexpression of PARP9 could induce type I IFN production in PARP9 and MAVS DKO BMDC after sensing dsRNA or reovirus infection." (PMID 33976210, 2021). "Compared to PARP9 and MAVS DKO BMDC, MAVS KO produced significantly more IFN-α and IFN-β in response to stimulation with intracellular poly (I:C) or reovirus infection." (PMID 33976210, 2021). "Additionally, MAVS KO or both PARP9 and MAVS DKO abrogated IL-6 production in response to intracellular poly I:C or reovirus infection, while PARP9 KO did not affect IL-6 production compared to WT BMDC." (PMID 33976210, 2021). "Knockdown of either PARP9 or MAVS reduced the production of IFN-α and IFN-β in human MDDC in response to LPIC or reovirus infection, but not to dsDNA HSV-60 or cGAMP treatment." (PMID 33976210, 2021). "However, overexpression of PARP9 in PARP9 and MAVS DKO BMDC did not affect the IL-6 production in response to intracellular poly I:C or viral dsRNA Reo1198 or reovirus infection." (PMID 33976210, 2021).
tuberculosis (2 papers, 2023). A chronic, recurrent infection caused by the bacterium Mycobacterium tuberculosis. "Of note, Parp9-deficient mice are susceptible to M. tuberculosis infection and exhibited increased TB pathology, elevated cGAS, 2′3′-cyclic GMP-AMP (cGAMP), and type I IFN expression, and upregulation of complement and coagulation pathways." (PMID 37200107, 2023). "We next tested the hypothesis that excess IFN-β expression mediates the increased TB susceptibility in Parp9–/– M. tuberculosis–infected mice." (PMID 37200107, 2023). "The increased M. tuberculosis susceptibility in Parp9–/– mice was type I IFN dependent, as blockade of IFNAR signaling reversed susceptibility to TB." (PMID 37200107, 2023). "Therefore, we assessed myeloid cell accumulation during early and chronic TB in B6 and Parp9–/– M. tuberculosis–infected mice." (PMID 37200107, 2023). "Although PARP9 mRNA expression is significantly increased in progressive tuberculosis (TB) in humans, its participation in host immunity to TB is unknown." (PMID 37200107, 2023). "PARP9 is expressed by macrophages within TB granulomas and required for M. tuberculosis control." (PMID 37200107, 2023). "Using M. tuberculosis infection of Parp9-deficient mice, we demonstrate that, unlike a virus-induced effect, there was an important negative regulatory role for Parp9 in DNA damage, cyclic GMP–AMP synthase (cGAS) expression, and type I IFN production during TB." (PMID 37200107, 2023). "Thus, we propose a model in which PARP9 induction during M. tuberculosis infection limits type I IFN, possibly via inhibition of a negative feedback loop, whereas during TB progression, PARP9 levels increase to modulate type I IFN signaling to limit M. tuberculosis susceptibility." (PMID 37200107, 2023).